GLI1 (GLI family zinc finger 1)
Diseases named in the same sentence as GLI1 in open-access papers (continued):
Sharing a sentence is not in itself a finding about the gene and the disease.
cancer (continued). "The percentage of cells with nuclear and cytoplasm staining of GLI1 was higher in cancer tissues than that in the adjacent normal tissues." (PMID 28399898, 2017). "Deregulation of Hh self-renewal pathway signaling, through GLI1 and GLI2 activation, has been linked to cancer stem cell generation and therapeutic resistance in MM18–20 and other hematopoietic malignancies." (PMID 29203771, 2017). "To examine GLI1 gene expression across different cancer types, we searched the cBioPortal, the most comprehensive Cancer Genomics database, from Memorial Sloan-Kettering Cancer Center." (PMID 28562331, 2017). "We found activation of the GLI1 signaling axis in acquired resistant cancer cells to 5-FU treatment." (PMID 28413604, 2017). "In this study, we revealed that the residual cancer cells following treatment with chemotherapeutic reagent cisplatin have elevated expression of hedgehog target genes GLI1, GLI2 and PTCH1, suggestive of hedgehog signaling activation." (PMID 28404967, 2017). "In this regard, Hh pathway antagonists include the SMO and GLI-1 proteins as the main targets for therapeutic schemes against cancers of epithelial origin." (PMID 28948003, 2017). "Taken together, we propose that a dual targeting approach combining a DYRK1B antagonist with an inhibitor of the PI3K/mTOR/AKT pathway has a pronounced impact on the GLI1 oncoprotein and exerts strong cytotoxic effects in cancer cells." (PMID 27903983, 2017). "Cancer signaling transduction can recapitulate dysregulated developmental signaling, so understanding mechanisms of Hh/Gli1 pathway regulation is critical to developing therapeutic targets for the cancer therapy." (PMID 28562331, 2017). "We have evidence to support that GLI1 is critical for maintenance of putative cancer stem cells through direct regulation of ABCG2." (PMID 28404967, 2017). "MEOX2 and RNA Pol II occupancy on the GLI-1 gene promoter was differentially enriched, likely correlating with different clinical parameters such as overall survival time and/or cancer drug response." (PMID 28978016, 2017). "SHH/GLI1 signaling pathway has been characterized as a NF-κB target pathway that promotes NF-κB-mediated apoptosis resistance in cancers." (PMID 28446712, 2017). "GLI1 plays a critical role in numerous types of cancer, and it promotes cancer stem cell self-renewal by inducing SNAIL expression." (PMID 29254217, 2017). "We found that elevated GLI1 signaling axis is responsible for 5-FU resistance both in cultured cell lines and in relevant cancer patients." (PMID 28413604, 2017). "It has been reported by several published studies that GLI1 regulates integrins in different cancer models." (PMID 28380428, 2017). "In a cohort of 415 cancer specimens, we found that 7 out of 12 (>50%) patients with high GLI1 transcript had relapsed cancer whereas 102 out of 310 patients with low GLI1 expression had relapsed cancer." (PMID 28404967, 2017). "GLI1 has also been shown to exhibit cancer stem cell property by overexpressing stem cell markers like OCT4, Nanog and Sox2." (PMID 28380428, 2017). "The selective GLI1/2 inhibitor GANT61 has shown high anti-cancer efficacy in in vitro studies as well as in animal models but only few data exist on the compounds’ pharmacokinetics." (PMID 28418873, 2017). "In this study, we identified that PTTG1 acted as a promoter in inducing EMT and cancer metastasis in ESCC via activating GLI1, an important factor of the HH-GLI signaling pathway." (PMID 29190924, 2017). "While GLI1 knocking down reduces the putative cancer stem cell population, ectopic expression of GLI1 increases this population." (PMID 28404967, 2017). "In addition, the underlying mechanisms of Gli1 inhibition by itraconazole are largely unknown, which also need to be explored in the further studies in order to better understand the molecular basis of itraconazole action in cancer cells." (PMID 28399898, 2017).
cancer (continued). "GANT-61, an antagonists of GLI1, appears to be highly effective against human cancer cells in vitro and in xenograft mouse models." (PMID 27275540, 2017). "In MM, here we demonstrate that malignant regenerative capacity is associated with ADAR1-mediated recoding of the self-renewal agonist GLI1, a pathway which has therapeutic potential in cancer while sparing normal stem cell maintenance." (PMID 29203771, 2017). "In ER-positive breast cancers, Gli1 promotes cancer stem cell (CSC)-like properties enhancing invasion and EMT." (PMID 26988232, 2016). "The stem cell biomarkers CD133, ALDH-1 as well as SHH and its downstream effector Gli-1 are involved in cancer stem cell self-renewal, clonogenicity, tumorigenicity, metastasis and drug resistance of numerous solid cancers, including PDAC." (PMID 27281617, 2016). "This study revealed the novel mechanism for the suppressive roles of WW45 in the cancer progression by negatively regulating Hedgehog/Gli1 signaling." (PMID 27661123, 2016). "Together, these data identify DYRK1B as possible therapeutic target to overcome SMO-inhibitor resistance in GLI1-dependent cancer cells." (PMID 26784250, 2016). "Recently, Gli1 has been reported to be a key regulator of various cancer biologies and genes expressions." (PMID 27863385, 2016). "Genetic and chemical inhibition of DYRK1B in human and mouse cancer cells resulted in marked repression of HH signaling and GLI1 expression, respectively." (PMID 26784250, 2016). "It has been thought that either the canonical or non-canonical Hh signaling pathway induces the expression of GLI1 and contributes to the nuclear accumulation and transcriptional activity of GLI1 in cancer cells." (PMID 26744317, 2016). "Two direct SMO antagonists, the steroidal natural product cyclopamine and the anti-cancer drug vismodegib, blocked Gli1 activation by MβCD:cholesterol." (PMID 27705744, 2016). "Given the importance of GLI1/2 in the SHH pathway on promoting EMT and metastasis, blockade of GLI1/2 is a candidate for cancer treatment." (PMID 27043642, 2016). "The frequently over-expressed Gli1 strongly triggers the carcinogenesis and dissemination in various cancer models." (PMID 26899488, 2016). "A meta-analysis which combined a wide spectrum of carcinomas demonstrated the correlation between Gli-1 expression and poor prognosis." (PMID 27634907, 2016). "The percentage of cells displaying nuclear GLI1 staining positively correlated with ErbB2 positivity (p = 0.027) in the carcinoma samples." (PMID 26843616, 2016). "The majority of investigations established potent evidence suggesting an unfavorable impact of Gli1 abnormality on clinical prognosis in a wide spectrum of carcinomas." (PMID 26899488, 2016). "Nuclear expression of GLI1 was observed in 33/51 (65%) carcinoma samples, including 3/10 (30%), 23/31 (74%) and 7/10 (70%) G1, G2 and G3 tumors, respectively." (PMID 26843616, 2016). "Given the importance of Shh–GLI1 pathway in cancer, some therapeutic approaches, focused on the blocking of this pathway, have been developed over the years." (PMID 26258070, 2015). "When Gli1 was activated by mTOR signalling through the SMO-dependent canonical pathway, S6K1-mediated Gli1 phosphorylation prevents Gli1 from SuFu-mediated inhibition in the cancer cells." (PMID 26218750, 2015). "Recently, studies in several human cancers have shown that GLI1 expression is independent from HH ligand and canonical intracellular signaling through PTCH and SMO." (PMID 26633513, 2015). "The increased Gli1 expression was evident observed only in the cancer cells with enlarged cell nuclei (arrows), located in the identical regions where Cul4A was overexpressed." (PMID 26218750, 2015). "Critical analysis of GLI1 and hTERT relationship in both normal and cancer cells of different lineages are needed to further establish GLI1’s role in carcinogeneis." (PMID 26633513, 2015).
cancer (continued). "DNA repair is frequently dysregulated or modified in cancer, making it important to analyze the impact of GLI1 on the differential regulation of these DNA repair mechanisms." (PMID 26633513, 2015). "Taken together, JIB-04 promotes the degradation of GLI1 in several human cancer cell lines and inhibits Hh signalling in vitro and in vivo." (PMID 26310823, 2015). "GLI1 has diverse functions including regulation of epigenetic methylation, cancer stem cells, hypoxia and human telomerase." (PMID 26633513, 2015). "Studies also shown that Gli1 inhibition induces cell-cycle arrest by promoting p21 transcriptional activity in human cancer cells 22,23." (PMID 26218750, 2015). "Specific cancer therapies to inhibit both the relevant oncogenes and GLI1 should be validated to design more effective treatment strategies." (PMID 26633513, 2015). "There is a truncated GLI1 (tGLI1) that is slightly smaller at 155 kDa and has only been found in tumors where it promotes an aggressive cancer phenotype." (PMID 26633513, 2015). "Pathway-specific inhibitors like AKT inhibitors, PI3K inhibitor can also be used to target cancer cells in conjunction with GLI1 inhibitors." (PMID 26633513, 2015). "For example, the EGFR and MAPK signaling pathways promote the nuclear localization and transcriptional activity of GLI1 protein in melanoma and other cancer cells." (PMID 25918934, 2015). "Among the three GLIs, GLI1 was found to be the most significant target for cancer therapy, because its activation was found in many cancers by both HH signaling dependent and independent mechanisms." (PMID 26633513, 2015). "Failure to terminate HH/GLI signaling, which occurs in cancer, leads to an amplified and persistent increase in GLI1 and GLI2 activity." (PMID 24962990, 2014). "The 130-kDa GLI1 isoform was quantitated and non-cancer ovarian samples had an average signal of 0.066." (PMID 24366538, 2014). "Eberl and colleagues demonstrated EGFR and HH act together to promote cancer cell proliferation by modulating gene expression through a GLI1-dependent mechanism." (PMID 25352983, 2014). "Histological analysis with NSCLC mouse tissue demonstrated that CDO was expressed in advanced grade of the cancer, and precisely co-localized with GLI1." (PMID 25369201, 2014). "While there is evidence for a dual role of GLI1 in PDAC, this phenomenon has yet to be linked with other cancer types." (PMID 25352983, 2014). "Compounds 1 and 4 showed strong inhibition of GLI1 transcriptional activity, and exhibited cytotoxicity against cancer cell lines with an aberrant activation of Hh signaling." (PMID 24454566, 2014). "Activation of Wnt/β-catenin and Hedgehog/Gli1 signalings results in overexpression of downstream c-Myc and cyclin D1, which are involved in cancer cell proliferation." (PMID 25386960, 2014). "The results indicate the importance of GLI1 signaling in these cells, which further extended to a panel of claudin-low cancer cell lines." (PMID 25252859, 2014). "Activation of both Wnt/β-catenin and Hedgehog/Gli1 signaling pathways results in the over-expression of cancer-related genes such as cyclin D and Myc, which are involved in cancer development." (PMID 25386960, 2014). "In multiple human cancer cell lines including colon, prostate and brain, suppression of GLI1 and GLI2 expression using GANT61, a small molecule inhibitor resulted in reduced expression of hTERT mRNA, protein and enzyme activity." (PMID 24086482, 2013). "In the future, defining Shh and Gli1 signatures in both, cancer epithelial and stromal cells will be relevant for a more accurate and comprehensive study of Hedgehog signaling in NSCLC." (PMID 23667589, 2013). "Emerging data from many human tumors have suggested that Hedgehog–Gli1 signaling regulates cancer stem cells." (PMID 24331293, 2013). "GLI1-knockout experiments showed that suppression of this transcription factor compromises proliferation, invasion and migration of cancer cells." (PMID 23969837, 2013).
cancer (continued). "It is known that GLI1 proteins are mediators of more than the Hh signaling pathway, and overexpression of GLI1 has been reported in several types of human cancer." (PMID 23861764, 2013). "One of the major signalling pathways activated by Ras is the ERK pathway, and Ras-MEK signalling plays an important role in GLI1 regulation of human cancer cells." (PMID 23436775, 2013). "Recently, some cancer-related RNA editing targets were discovered such as antizyme inhibitor 1 (AZIN1) and glioma-associated oncogene 1 (GLI1)." (PMID 23737728, 2013). "We found that the levels of Shh and Gli1 proteins were higher in 6 Gy irradiated cancer cells than other doses treated cancer cells." (PMID 23762282, 2013). "This analysis confirmed that GLI1 was significantly overexpressed in all HNSCC samples compared to normal mucosa from non-cancer affected individuals, with a mean fold changes of 3.1 above normals (one-sided p-value of 0.001 from a t-test)." (PMID 24223768, 2013). "To complement these overexpression studies, we evaluated the effect of suppression of GLI1 on the cancer phenotype by transfecting the endogenously high GLI1-expressing SNU398 cells with GLI1 ASO." (PMID 23185371, 2012). "In colorectal cancer, Gli1 was shown to inhibit the proliferation of cancer cells by suppressing activation of the Wnt signalling pathway." (PMID 22550422, 2012). "D-finder also pinpointed highly similar D-sites in the paralogous transcription factors Gli1 and Gli2, proteins that (like Gli3) are important in regulators of stem cells and development, and which are dysregulated in several types of cancer." (PMID 20865152, 2010). "Human GLI1 gene amplification is also uncommon in most cancers even though it was initially identified as an amplified gene in a cancer cell line." (PMID 21119888, 2010). "Additional evidence suggests a potential involvement of GLI1 in therapeutic response of human cancers." (PMID 21119888, 2010). "Hedgehog-Gli1 signaling has also been implicated in epithelial-to-mesenchymal transition (EMT), and increases in the levels of pathway components (particularly Gli1) parallels the progression of carcinoma stem cells to metastatic states." (PMID 24281215, 2010). "Consistent with previous studies, it was found that various levels of GLI1 were expressed in the cell lines, indicating that the HH/GLI1 pathway plays a pivotal role in NSCLC cancer cell progression." (PMID 19575820, 2009). "Although the functional and clinical significance of the Hh pathway remains to be elucidated, we suggest that Gli-1 expression is a link between relapse and CRT-resistant cancer cells, and is thus a potential diagnostic biomarker and therapeutic target." (PMID 18475300, 2008). "In the current study, even patients with Gli-1 nuclear (±) expressing cancers (2.9%) died from distant metastasis within a few months." (PMID 18475300, 2008). "This multifaceted inhibition of the SHH/GLI1 pathway translates into tangible anti-cancer effects, including suppressed cell proliferation, colony formation, and migration, and increased apoptosis, partially mediated through the mitochondrial pathway, as evidenced by an increased Bax/Bcl2 ratio." (PMID 40227413, 2025). "Our study also indicates that hyperthermia can be a promising therapy to GLI1 activated cancers." (PMID 41497797, 2025). "However, they occurred independently of tissue invasion (perineural, lymphovascular, fat, bone, muscle, and mucous acini) and proteins related to the HH pathway (SHH, IHH, SMO, and GLI‐1), which contributed to the morphogenesis of this rare cancer." (PMID 40930949, 2025). "A TIMER database was used to analysis the expression of GLI1 in various cancer." (PMID 40255562, 2025). "Given its pivotal role, GLI1 serves as a promising therapeutic target for cancer." (PMID 39829890, 2025). "Additionally, the R package was utilized to further analyze the expression levels of GLI1 across 33 cancer types in the TCGA database." (PMID 39483334, 2024).
cancer (continued). "While studies investigating the role of GLI family genes in cancer have primarily focused on GLI1, the contribution of GLI2/3 to tumorigenesis, especially in the context of the tumor immune microenvironment (TIME), remains largely unknown." (PMID 38498906, 2024). "Targeting GLI1/2/3 may represent a promising therapeutic approach for treating cancer patients in the future." (PMID 38498906, 2024). "In addition, GLI1 can be activated by different oncogenic pathways thus highlighting the relevance to unveil the molecular mechanisms that govern its misregulation in cancer." (PMID 38062245, 2024). "Additionally, univariate Cox analysis of disease-specific survival (DSS) revealed that GLI1, GLI2, and GLI3 were risk factors for patients with 10, 7, and 5 types of cancer, respectively." (PMID 38498906, 2024). "Because transcriptional programs induced by Hh signal depend on the GLI transcription factor, we tested whether GLI-1 mediates the re-expression of KRAS in cancer cells treated with a KRASG12C inhibitor." (PMID 38225225, 2024). "Similarly, GLI1, GLI2, and GLI3 were identified as prognostic risk factors for patients with 9, 8, and 6 types of cancer, respectively, using progression-free interval (PFI) analyses." (PMID 38498906, 2024). "This study may also facilitate future research efforts focused on GLI1/2/3 as promising targets for cancer immunotherapy." (PMID 38498906, 2024). "These properties make GLI1 a promising target for cancer treatment." (PMID 39483334, 2024). "Disruption of the Sonic Hedgehog (Shh)–GLI1 pathway has been shown to result in tumorigenesis and the emergence of aggressive traits, including disease progression, metastasis, and therapy resistance, in various types of cancer." (PMID 37894854, 2023). "Using Western blot, the authors found that, in HT-29 CD133+ cells, knockdown of Prx2 decreased and overexpression of Prx2 increased the expression of SMO and Gli1 proteins, suggesting Prx2 might regulate cancer stem cell properties via Hedgehog/Gli1 pathway." (PMID 37237480, 2023). "GLI1, a transcriptional factor, is a key molecule in the hedgehog (HH) signaling pathway, and the dysregulated HH pathway is involved in the development and progression of many cancers, such as breast, pancreatic, and prostatic cancers." (PMID 37165307, 2023). "Gli1 is also a potential cancer stem cells (CSC) marker in PCa." (PMID 38008751, 2023). "GLI1 inhibition facilitates multiple therapeutic approaches in distinctive cancer types." (PMID 37149646, 2023). "Overall the genomic landscape was stable, with pathogenic or likely pathogenic alterations being identified in 51 cancer genes, with 9 (18%) of them showing alterations being recurrent across different samples (MYCN, CDKN2A/2B, CDK4, GLI1, AKT1, IGF2, MED12, NCOR2)." (PMID 37730754, 2023). "Furthermore, GLI1 and GLI2 are the main transcriptional effectors, and their constitutive activation is the most important risk factor for cancer development and progression." (PMID 37504255, 2023). "Previous studies found that the Hh pathway genes, SMO and GLI1, are regulated by bFGF, and the SMO receptor is responsible for maintaining normal embryonic development and that abnormalities in this protein are associated with cancer." (PMID 37139482, 2023). "In addition, GLI-1 is an important therapeutic target in cancer, including through its interaction with SUFU." (PMID 35501860, 2022). "CAFs are not only a potential source of Hh ligands in the cancer stroma but may also respond to H signaling through nuclear Gli-1 activation." (PMID 36517618, 2022). "We suggest that this MAPK-mediated SUFU release might be an important component of the molecular mechanism by which MAP kinases activate GLI1 in cancers and other pathological scenarios." (PMID 35831023, 2022). "However, only a few studies have explored the involvement of Hh-GLI1 signaling and metabolic reprogramming in cancer; the reports have been contradictory." (PMID 36046646, 2022).